BRCA2 (BRCA2 DNA repair associated)
Diseases named in the same sentence as BRCA2 in open-access papers (continued):
Sharing a sentence is not in itself a finding about the gene and the disease.
cancer (continued). "Individuals with pathogenic variants of BRCA1 and BRCA2 are at higher risk of breast, ovarian, pancreatic and many other cancers." (PMID 39507757, 2024). "BRCA1 and BRCA2 are two tumor-suppressor genes frequently mutated in breast, ovarian, prostate, pancreatic, and other cancers." (PMID 39007266, 2024). "Cancer cells from patients who carry a disease-causing BRCA1 or BRCA2 mutation are incapable of repairing double-strand DNA breaks via the homologous recombination (HR) repair pathway." (PMID 38398132, 2024). "In the overall MaBC and FBC cohorts, we compared mutational prevalence in cancer susceptibility genes (CSG) (ATM/BRCA1/BRCA2/CHEK2/PALB2)." (PMID 39049124, 2024). "Post-treatment cold tumors also acquired more cancer-specific mutations (i.e., BRCA2, TPR, OMD, RANBP2, EP300)." (PMID 38714665, 2024). "Talazoparib and Olaparib are both oral PARP inhibitors that interfere with the PARP enzyme, making it more difficult for cancer cells with BRCA1 or BRCA2 mutations to repair DNA damage, reducing the likelihood of cancer survival and progression." (PMID 38327984, 2024). "On a population level, testing for BRCA1, BRCA2, and other cancer predisposition syndromes will also help to identify individuals at high risk of other cancers, such as breast and ovarian cancer." (PMID 38583453, 2024). "Mutations in the breast cancer gene 1 (BRCA1) and breast cancer gene 2 (BRCA2) genes significantly increase the risk of breast and ovarian cancers." (PMID 39767566, 2024). "A study in 2003 used a cancer-predisposing BRCA2 mutation (Y42C) to investigate its interaction with RPA." (PMID 38397158, 2024). "Researchers previously identified breast cancer susceptibility gene 2 (BRCA2) by performing genetic linkage analysis with families affected by early-onset breast cancer who did not carry BRCA1 mutations." (PMID 38773604, 2024). "All three BRCA2-mutated patients showed advanced disease and a significant family history of cancers associated with the HBOC syndrome." (PMID 38974244, 2024). "Although 58.3% of women with a mutation had several relatives with various types of cancer, segregation analysis was performed in some families with index cases having P/LP variants in BRCA2, ATM, and PALB2 genes." (PMID 38890714, 2024). "PARP inhibitors were originally developed based on synthetic lethality in BRCA1/BRCA2-deficient cancer cells which have impairment for the double-strand break repair." (PMID 39117659, 2024). "Despite the HRD phenotype, WGS analysis revealed the sporadic nature of the cancer, with two somatically acquired mutations: a frameshift insertion and a combined loss of heterozygosity in the BRCA2 gene." (PMID 39138315, 2024). "PEO1 and PEO4 cells are isogenic with a difference in the status of BRCA2 (Breast And Ovarian Cancer Susceptibility Protein 2), a HR protein." (PMID 39659585, 2024). "We show that BRCA1 and BRCA2 mutation statuses differentially impact the regulation of the Wnt/β-catenin signaling pathway, a major effector of cancer initiation and progression." (PMID 39028933, 2024). "One of the paradoxes concerning BRCA2 is the fact that its inactivation affects genetic stability and is deleterious for cellular and organismal survival, while BRCA2-mutated cancer cells adapt to this detriment and malignantly proliferate." (PMID 37934606, 2024). "Familial cases of breast and ovarian cancer often involve mutations in the tumor suppressors BRCA1 (breast cancer type 1 susceptibility protein) and BRCA2 (breast cancer type 2 susceptibility protein)." (PMID 39767562, 2024). "Breast cancer 1 (BRCA1) and BRCA2 loss of heterozygosity (LOH) is a paradigmatic event in cancer initiation." (PMID 38557488, 2024). "Follow-up studies will be imperative to delineate the molecular differences underpinning distinct fork recovery mechanisms in BRCA1- versus BRCA2-deficient cancer cells." (PMID 38943334, 2024).
cancer (continued). "We also observed that ATM and BRCA2/FANCD1 consistently exhibit the highest mutation rates across different tissue-specific cancer types, a pattern corroborated by other mutational screening studies." (PMID 39421870, 2024). "Individuals who carry BRCA1 or BRCA2 pathogenic variants are recommended to have extensive cancer prevention screening and risk-reducing surgeries." (PMID 37864742, 2024). "How cancer cells with BRCA2 deficiency can endure these pressures and malignantly proliferate remains to be elucidated." (PMID 37934606, 2024). "BRCA1 and BRCA2 stand out as the predominant genes associated with this specific cancer type compared to others." (PMID 38672725, 2024). "In BRCA2-deficient cancer cells, MUS81, a structure-specific endonuclease, and the POLD3 protein cooperate to facilitate a Break-Induced Replication (BIR)-like mechanism of fork restart." (PMID 38943334, 2024). "Up to 40–80% of hereditary breast and ovarian cancers are due to BRCA1/BRCA2 germline mutations, and these genes are affected by germline or somatic genetic alterations in up to 8% of cancers." (PMID 39198848, 2024). "The contribution of BRCA1 and BRCA2 to cancer has been extensively studied, as families with these mutations show clustering of cancers in men." (PMID 39364320, 2024). "In cancer cells deficient in the BRCA2 complex, the alternative HR pathway involving RAD52 must step up to continue HR, but most importantly, it must continue to repair the broken DNA." (PMID 38397158, 2024). "This leads to the death of cancer cells with BRCA1/BRCA2 mutations or homologous recombination deficiency." (PMID 39175508, 2024). "Genetic factors play a role too, with inherited mutations like BRCA1 and BRCA2 increasing susceptibility to certain cancers." (PMID 39463536, 2024). "Depletion of key HR components BRCA2 or ataxia telangiectasia mutated (ATM) in cancer cells conferred up to 12-fold increased sensitivity to the LP-184." (PMID 38630886, 2024). "Two nonsense variants, specifically BRCA1 c.5470_5477del and BRCA2 c.5682 C > G, were identified in both healthy individuals and cancer patients." (PMID 38566028, 2024). "Our research suggests that PP2A inhibition to reactivate the SAC can be an attractive synthetic lethal agent for the treatment of cancer patients with BRCA2 mutations." (PMID 37934606, 2024). "Here, we report the ascertainment of the BRCA2 pathogenic variant c.517-2A>G in both clinical care in cancer families, and research volunteers, from Shetland." (PMID 39438716, 2024). "All BRCA2 variants detected in male cancer patients have been observed to be distributed along the entire BRCA2 gene sequence." (PMID 38974244, 2024). "While BRCA1/BRCA2 mutations modestly increase tumor mutation burden, their impact on the copy number landscape of cancer is notably more substantial." (PMID 39198848, 2024). "Among these cancer susceptibility genes, mutations in the BRCA2 gene occurred at a low frequency in patients with CCA, mainly in the intrahepatic locus." (PMID 37966669, 2024). "Deficiency in DSB repair mediated by BRCA1 and BRCA2 can lead to the proliferation of cancer cells due to the accumulation of driver mutations." (PMID 38666816, 2024). "Many susceptibility genes, notably BRCA1, BRCA2, and the mismatch repair genes, are associated with multiple types of cancer, 2 but in general, cancer pleiotropy is poorly understood." (PMID 39209703, 2024). "Breast cancer susceptibility gene 1 (BRCA1) and breast cancer susceptibility gene 2 (BRCA2) are critical components in maintaining genomic stability through their roles in the homologous recombination (HR) pathway." (PMID 39199310, 2024). "Consistent with this, individuals with mutations in BRCA1 and BRCA2 harbor a high risk of developing various types of cancer, including breast, ovary, prostate, esophagus, stomach, and uveal cancers." (PMID 39595558, 2024).
cancer (continued). "Eleven women from four Shetland families presenting with BRCA2-related cancers were found to have the BRCA2 c.517-2A>G variant, as part of routine clinical care." (PMID 39438716, 2024). "With this in mind, several RAD52 inhibitors have been developed and show promising results in killing BRCA2-deficient cancer cells." (PMID 38658755, 2024). "BRCA1 has been implicated in promoting autophagy under cellular stress conditions, while BRCA2 deficiency has been associated with impaired autophagy flux, potentially contributing to cancer development and treatment resistance." (PMID 39199310, 2024). "Among patients with FA, the highest cancer risks are observed in patients with biallelic pathogenic variants in BRCA2 or PALB2." (PMID 38685107, 2024). "Based on this initial model, PARPis have been found selectively toxic to cancer cells harboring BRCA1 or BRCA2 (BRCA1/2) mutations or showing HR deficiency." (PMID 38961202, 2024). "Similar results have been reported in multiple studies, implying that BRCA1 and BRCA2 were associated with the early onset of cancer." (PMID 38817903, 2024). "Inherited mutations that impair HDR (e.g., BRCA1 and BRCA2 variants) are associated with elevated cancer risk, including early-onset breast cancer." (PMID 38824133, 2024). "One primary pathway involves secondary or “reversion” mutations in BRCA1 or BRCA2 genes that restore the functional reading frame, thereby reinstating homologous recombination repair capabilities in cancer cells." (PMID 39272683, 2024). "The O/E for all cancer types were 2.8 for BRCA2 and 2.85 for FANCD2, with the risk for BC specifically indicated as 11.0 and 16.3, respectively." (PMID 38814507, 2024). "In individuals with family history of cancer, 5–10% carries PVs in BRCA2 gene and 1% in BRCA1 with a risk of developing PC of 5 and 10%, respectively." (PMID 38974244, 2024). "For example, it has been reported that the risk of developing cancer varies among individuals with a BRCA2 variant." (PMID 37956396, 2024). "BRCA1 and BRCA2 are tumor suppressors in several cancers and have been implicated in DNA repair in response to DNA breaks, transcription regulation, and cell growth control." (PMID 39338204, 2024). "Several PARP inhibitors gained FDA approval for treating cancers that harbor mutated BRCA1 or BRCA2 genes." (PMID 37510250, 2023). "All PVs observed within BRCA2 were deletion or duplication events which significantly disrupt gene function (c.3170_3174del, c.4787del, c.5557dup), these appeared only in cancer patients and high-risk patients, with 5 of 7 BRCA2 PV carriers affected." (PMID 37306523, 2023). "Deficiencies of IRF9 lead to a significantly greater risk of severe COVID-19 illness and impair cancer-protective effects of BRCA2 gene activity." (PMID 37626783, 2023). "BRCA and BRCA2 are high-penetrance cancer susceptibility genes involved in homologous recombination DNA repair that are mutated in 5% of unselected BC patients." (PMID 37148499, 2023). "It is already established that the mutation of BRCA2 is associated with unrepaired DSBs leading to genomic instability and cancer progression." (PMID 37170264, 2023). "Combining exemplary homozygous hypomorphic Brca2/Fancd1 and Rad51c/Fanco mutations in mice phenocopies human FA with bone marrow failure, rapid death by cancer, cellular cancer-drug hypersensitivity and severe replication instability." (PMID 36906610, 2023). "This structural plasticity of BRCA2 protein is attributable to the intrinsically disorder regions that are a hallmark of cancer associated proteins." (PMID 37020472, 2023). "Targeting BRCA1- and BRCA2-deficient tumors through synthetic lethality using poly(ADP-ribose) polymerase inhibitors (PARPi) has emerged as a successful strategy for cancer therapy." (PMID 37554969, 2023). "Those with personal histories of cancer or positive BRCA2 mutations had increased worry of developing cancer at baseline." (PMID 37684686, 2023).
cancer (continued). "It is noteworthy that cells and organisms survive with mutations in ATM or other components required for HRR, such as BRCA1 and BRCA2, but at the expense of genomic instability and cancer predisposition." (PMID 37627523, 2023). "We note with interest the diversity of BRCA1 and BRCA2 variants within our cancer patient group, and the enrichment of BRCA2 VUS in cancer patients." (PMID 37306523, 2023). "To evaluate the molecular profile of C220, we evaluated changes in global gene expression by RNA-seq following C220 treatment in HR-proficient breast (MCF7) and ovarian (A2780), and HR-deficient breast (HCC1569; BRCA2 mut) cancer cell lines." (PMID 37861290, 2023). "In our study, in a selected cohort of subjects characterized by a common local origin and a cancer family history, we identified a BRCA2 PV that was further analyzed and correlated to the risk of PC onset." (PMID 37046793, 2023). "Genetic factors represent one of the major driving causes of OC onset, where the tumor-suppressor BRCA1 and BRCA2 gene alterations are the most associated with the increased cancer susceptibility." (PMID 38069422, 2023). "BRCA1 and BRCA2 mutations responsible for the majority of homologous recombination deficient (HRD) cancers are prevalent in solid tumors of the breast, ovaries and prostate." (PMID 36792656, 2023). "The bias towards BRCA1/BRCA2 is in fact aligned with the higher cancer risk associated with the variants occurring in these genes." (PMID 36896237, 2023). "Linked-read WGS also identified single-strand annealing as a repair pathway that is specific to BRCA2 deficiency in human cancers." (PMID 37587346, 2023). "The proportion of germline SV mutations in BRCA1 and BRCA2 was markedly elevated in OC (BRCA1, 3.4%; BRCA2, 1.7%) and PC (BRCA2, 2.2%) compared to other cancers, as was the proportion of germline SV mutations in the HR genes RAD51C and RAD51D in OC." (PMID 37821580, 2023). "Individuals with HBOC are heterozygously mutated in either BRCA1 or BRCA2, and the cancer‐initiating cells in these patients usually undergo loss of the wild‐type BRCA1/2 allele, leading to homologous recombination defects." (PMID 36345163, 2023). "After excluding ineligible patients, a total of 89 cancers in 81 patients with BRCA1-positive mutations and 83 cancers in 71 patients with BRCA2-positive mutations were included." (PMID 36905492, 2023). "All men carrying BRCA1 or BRCA2 mutations should start cancer screening at the age of 40 with yearly PSA and consider the same in men with BRCA1, ATM, HOXB13, and DNA MMR mutations." (PMID 37021836, 2023). "Although it is an indispensable event for some cancers, BRCA2 mutations appear to be biologically neutral in a proportion of other cancers, including AVC." (PMID 37274233, 2023). "Since BRCA1 and BRCA2 are involved in DNA repair, mutations in these genes can cause genetic errors leading to cancer." (PMID 37445860, 2023). "BRCA-associated HBOC is also characterized by an increased risk of other cancers such as male BC, prostate, and pancreatic cancer, primarily in individuals with BRCA2 P/LPV." (PMID 36980956, 2023). "Most cases of HBOC are caused by mutations in the breast cancer 1 (BRCA1) or breast cancer 2 (BRCA2) genes." (PMID 34989978, 2023).
cancer (continued). "Cancer risk management: This module offers generic information on how testing results can inform prevention and screening for cancers known to be associated with BRCA1/BRCA2-associated HBOC." (PMID 37760455, 2023). "After tumor progression, cancer genomic profiling testing using liquid biopsy revealed BRCA2 p.Gln3047Ter and p.Gln3047Tyr, with 48.9% and 0.37% allele frequency, respectively." (PMID 37361653, 2023). "BRCA2 variants were also significantly more frequent in persons with cancer (p = 9.82e−08), with a notable enrichment of BRCA2 VUS in these patients." (PMID 37306523, 2023). "Linking mutations in the BRCA1 and BRCA2 genes to the general mechanisms of genome stability and DNA repair is critical to ensure the rationalized choice of anti-cancer therapy." (PMID 36902416, 2023). "To validate our findings in another cancer cell line model, we tested Mirin sensitivity in HeLa control and BRCA2-deficient HeLa cells." (PMID 37446144, 2023). "Data on heterozygote PALB2 disease-causing variant carriers compared to BRCA1/BRCA2 carriers are still scarce in terms of both cancer incidence, spectrum of cancers and clinical outcomes." (PMID 37686625, 2023). "FA displays an autosomal recessive inheritance, but cancer risk is associated with some heterozygous mutations in the following genes: BRCA2 (FANCD1), BRIP1 (FANCJ), PALB2 (FANCN), RAD51C (FANCO), BRCA1 (FANCS)." (PMID 37239385, 2023). "Studies show that BRCA1 or BRCA2 dysfunction profoundly sensitize cells to poly-ADP ribose polymerase (PARP) inhibitors (PARPi) due to HR repair defects in BRCA1 or BRCA2-deficient cancer cells." (PMID 36794849, 2023). "Inheritance of a cancer causing pathogenic BRCA2 variant significantly increases the disease risk in mutation carriers." (PMID 37980415, 2023). "The content was updated to emphasize the association of BRCA1/BRCA2 variants with prostate, pancreatic, and possibly other types of cancer." (PMID 37760455, 2023). "Identifying BRCA1 or BRCA2 PV has important clinical implications in risk management and cancer treatment decisions." (PMID 38067403, 2023). "Of course, the probability of people suffering from cancer will also vary due to the different mutation locations in BRCA1 or BRCA2 genes." (PMID 36765522, 2023). "Both BRCA1 and BRCA2 are needed for HR and consequently cancer cell lines deficient in BRCA1 or BRCA2 are highly sensitive to PARP inhibitors." (PMID 37773077, 2023). "Recently, large‐scale analysis identified histone mutations in 3.8% of human tumor samples, a ratio similar to the mutations of known cancer‐associated genes such as BRCA2 and NOTCH1." (PMID 37255015, 2023). "Pathogenic variants in the BRCA1 and BRCA2 genes appear in different types of cancer, among which they are more frequently found in breast, ovarian, pancreatic, or prostate cancer." (PMID 37296748, 2023). "Loss-of-function (LOF) germline mutations in HRR genes, such as BRCA1 and BRCA2, significantly contribute to the elevated risk of cancer in heterozygous carriers." (PMID 37298484, 2023). "Several genome-wide screens have identified APE2 as a synthetic lethal target for deficiencies of BRCA1, BRCA2 or TDP1 in cancer cells." (PMID 36755963, 2023). "The model allows for personalising PCa risks on the basis of a consultand's age, detailed cancer FH, moderate- to high-risk BRCA2, HOXB13, and BRCA1 PVs, and a 268-SNP PGS." (PMID 36493335, 2023). "Extending clinical genetic screening from BRCA1 and BRCA2 to 13 established cancer predisposition genes almost doubles the diagnostic yield, which has implications for genetic counseling and clinical guidelines." (PMID 37563628, 2023).